PTTG1IP2 (PTTG1IP family member 2)
Tractability: Antibody: UniProt predicts a signal peptide or a membrane-spanning region.
Gene: Protein-coding gene on chromosome 7 (90,469,639 to 90,513,397, forward strand). Ensembl gene ENSG00000251154.
Subcellular location: Membrane
Gene Ontology:
Cellular component: membrane
Homologues: Orthologues: mouse Pttg1ip2 (49% identical), rat Pttg1ip2 (44% identical). Paralogues in human: PTTG1IP (21% identical).
Diseases named in the same sentence as PTTG1IP2 in open-access papers:
PTTG1IP2 is named in the same sentence as 2 diseases in open-access papers, as found by Europe PMC text mining. Sharing a sentence is not in itself a finding about the gene and the disease. The quoted sentences say what the papers report.
hepatitis B virus infection (1 paper, 2021). A viral infection caused by the hepatitis B virus. "Finally, out of the three SNVs uniquely present in the age-adjusted cohort, rs8014123 is associated with thyroid carcinoma (THCA), while rs10268928 in PTTG1IP2 Family member 2 (PTTG1IP2) is associated with hepatitis B virus infection." (PMID 34575070, 2021).
PTTG1IP2 also shares sentences with these, for which no sentence is quoted: thyroid carcinoma (1 paper).